TAL2 (TAL bHLH transcription factor 2)
Synonyms: TAL-2; bHLHa19
Tractability: No criterion of Open Targets' tractability assessment is met for any kind of drug.
Gene: Protein-coding gene on chromosome 9 (105,662,457 to 105,663,124, forward strand). Ensembl gene ENSG00000186051.
Subcellular location (Human Protein Atlas): Cytosol
Gene Ontology:
Molecular function: protein binding; DNA binding; DNA-binding transcription factor activity, RNA polymerase II-specific; RNA polymerase II cis-regulatory region sequence-specific DNA binding; protein dimerization activity
Biological process: regulation of transcription by RNA polymerase II
Cellular component: chromatin; nucleus
Genetic constraint (gnomAD): Loss-of-function variants: 1 observed, 3.28 expected, observed/expected ratio (o/e) 0.3, 90% interval 0.11 to 1.38. That is too few expected variants to judge how well the gene tolerates losing a copy. Missense variants: 114 observed, 133.55 expected, observed/expected ratio (o/e) 0.85, 90% interval 0.73 to 1. Synonymous variants: 48 observed, 55.26 expected, observed/expected ratio (o/e) 0.87, 90% interval 0.69 to 1.11.
Homologues: Orthologues: chimpanzee TAL2 (100% identical), rabbit TAL2 (94% identical), dog TAL2 (88% identical), mouse Tal2 (86% identical), rat Tal2 (85% identical), guinea pig TAL2 (81% identical), tropical clawed frog TAL2 (67% identical), zebrafish tal2 (56% identical). Paralogues in human: TAL1 (51% identical), LYL1 (48% identical), NHLH1 (30% identical), NHLH2 (30% identical).
Diseases named in the same sentence as TAL2 in open-access papers:
TAL2 is named in the same sentence as 18 diseases in open-access papers, as found by Europe PMC text mining. Sharing a sentence is not in itself a finding about the gene and the disease. The quoted sentences say what the papers report.
ovarian carcinoma (3 papers, 2014 to 2024). A malignant neoplasm originating from the surface ovarian epithelium. "When looking at Tal2, the higher expression was resolved in the F2 generation, but concern remains for the F1 generation as some studies have associated Tal2 with ovarian cancer, though usually due to decreased expression." (PMID 38791003, 2024). "Pluripotency markers OCT4, SOX2 with cancer markers BRCA1, BRCA2, ER, PR and HER2 in breast cancer iPSCs; Tal2, EGF, ILF3, UBI2I, BRCA1 and BRCA2 in ovarian cancer iPSCs were analyzed." (PMID 37479967, 2023). "Tumor tissue derived organoids and snap frozen tissues were analyzed for BRCA1, BRCA2, ER, PR and HER2 in breast cancer, Tal2, EGF, ILF3, UBI2I, BRCA1 and BRCA2 in ovarian cancer." (PMID 37479967, 2023).
leukaemia (1 paper, 2013). "Tal2 expression is linked to T-cell leukaemia, we also detected Tal2 expression in the erythroleukaemia cell line K562, and thus it might be involved in this form of leukaemia." (PMID 24086757, 2013). "The further analysis of Tal2 expression and function in the human system should reveal differences to the mouse model and shed light on the potential role of Tal2 in osteoclast related disease and leukaemia." (PMID 24086757, 2013). "Tal2, which belongs to the same family of transcription factors as Tal1 and Lyl1, is also involved in human leukaemia." (PMID 24086757, 2013). "Although Tal2 has an important function in development and leukemia, little is known regarding the regulation of Tal2 and its expression in different cell types." (PMID 24086757, 2013).
lymphoma (1 paper, 2012). A malignant (clonal) proliferation of B- lymphocytes or T- lymphocytes which involves the lymph nodes, bone marrow and/or extranodal sites.
ovarian diseases (1 paper, 2023). "More research is necessary to investigate this potential association between Tal2 expression and ovarian diseases." (PMID 37029425, 2023).
sarcoma (1 paper, 2023). A usually aggressive malignant neoplasm of the soft tissue or bone. "Whether this specific malignancy found in the previous study is associated with a higher expression of Tal2 as found in this study is still unknown, since sarcomas have a divergent molecular pathology compared to carcinomas." (PMID 37029425, 2023).
cancer (4 papers, 2014 to 2024). A tumor composed of atypical neoplastic, often pleomorphic cells that invade other tissues. "Although aberrant TAL2 expression may be involved in development of some cancers, TAL2 is essential for the normal development of the mouse brain." (PMID 24816818, 2014).
Tumor (3 papers, 2016 to 2023). "Among 3372 captured cells, a large group of RMC cells was identified along with TAMs and other CD45-expressing immune cells (Natural killers, neutrophils and T-cells), POSTN-expressing CAFs, and an unexpected population of tumour-associated TAL2/3 cells." (PMID 37236926, 2023). "Further evidence for this series of oncogenic events came from the fortuitous capture of tumour-associated TAL2/3 cells that displayed a pre-transformed state retaining TFCP2L1 activity, while at the same time showing MYC and YY1 activity accompanied by a hypoxia and stress signature." (PMID 37236926, 2023).
TAL2 also shares sentences with these, for which no sentence is quoted: acute lymphoblastic leukemia (2 papers); infection (2); T-cell acute lymphoblastic leukemia (2); Ataxia (1); autism spectrum disorder (1); breast carcinoma (1); chronic myeloid leukemia (1); epilepsy (1); neuroblastoma (1); neurodevelopmental disorder (1); thymic lymphomas (1).